CXCL10 (C-X-C motif chemokine ligand 10)
Diseases named in the same sentence as CXCL10 in open-access papers (continued):
Sharing a sentence is not in itself a finding about the gene and the disease.
infection (continued). "IL-8 is a key neutrophil chemoattractant, while CXCL10 promotes T-cell trafficking to infection sites." (PMID 41583233, 2025). "We quantified serum levels of IL-4, IL-6, IL-8/CXCL-8, IL-27, CCL-2, CXCL-9, CXCL-10, and IgG using Luminex and ELISA assays during the acute and subacute phases of infection." (PMID 40711072, 2025). "Similar to transcriptomic analyses, induction of MCP-2 and CXCL10 was more pronounced in infection-experienced study participants compared with the naive group after the prime vaccination." (PMID 38716734, 2024). "At 48 h of infection, the gene expression of CXCL10, TNF-α, IL-8, and IL-6 was increased up to 47.14-fold, 26.43-fold, 10.87-fold, and 3.45-fold, respectively, while the COX-2 gene was expressed 70.70-fold after 72 h of dengue viral infection." (PMID 39200005, 2024). "Chemokine-related genes CXCL9 and CXCL10 were significantly up-regulated in the early phase of infection, while CCL4 was significantly up-regulated in the late phase of infection." (PMID 39026675, 2024). "Peaks of activated T and NK cells, B cells, monocyte derived macrophages, CCL8—and CXCL10 production are clearly lower than at the initial infection event." (PMID 39695178, 2024). "On day 4 post infection, we found that in our model, Cxcr3 transcript levels were decreased in both infected Cxcl10+/+ and Cxcl10−/− mouse lung relative to the uninfected controls." (PMID 39803542, 2024). "As expected, the addition of ADP-heptose to ΔrfaE-infected DCs reduced the secretion of IFNα and CXCL10 as well as type I IFN signaling to the levels observed in H. pylori wt infections." (PMID 39288239, 2024). "CCL2 and CXCL10 transcripts were upregulated after 30 days and 60 days of infection, as were IFN-a, IFN-b, ISG15, and IFI16 transcripts." (PMID 38737767, 2024). "In contrast, SeVeGFP infection resulted in a significant release of IL-6 and CXCL10, albeit at ten-fold lower levels as compared to stimulation with a pro-inflammatory cocktail." (PMID 39351233, 2024). "Future studies will be necessary to dissect mechanisms that confer CXCL10-dependent host protection during early and late phases of infection." (PMID 39803542, 2024). "These innate differences between LNCaP and PANC-1 also influence the expression of rSFV-encoded transgenes, with Flt3L, CXCL10, and IFN-γ concentrations being notably higher in LNCaP than PANC-1 at 6 h post-infection." (PMID 38425844, 2024). "At 48 hours after infection, significant reductions in the mRNA expression levels of Cxcl9 and Cxcl10 were detected in the FP skin of CD1d-KO mice compared with WT mice." (PMID 39088280, 2024). "On the other hand, other chemokines involved in T cell trafficking such as Cxcl9 and Cxcl10 are highly expressed during the first few days of infection, as is their receptor Cxcr3." (PMID 38352492, 2024). "Both CXCL9 and CXCL10 control the spread of infection in the CNS through the recruitment of effector cells, such as phagocytes and lymphocytes, to the CNS." (PMID 38879567, 2024). "Intriguingly, orotracheal infection with a low dose triggered the induction of IFNβ1 and CXCL10 expression in the pulmonary lymph nodes, indicating the spread of SARS-CoV-2 from the trachea to these lymph nodes." (PMID 39599832, 2024). "In our study, we found that TLR7 was involved in the immunopathogenesis of infection with RABV, and the expression of CCL2, CXCL10 and IL-6 were significantly increased in the terminal stage of infection with RABV." (PMID 39273091, 2024). "Specifically, CXCL10 is primarily expressed on glia and recruits lymphocytes and phagocytes to inflamed areas to limit the spread of infection and as is the case with CXCL9, aids in T-cells responses to bacterial infection." (PMID 38879567, 2024). "Seven-day old BALB/c mice were infected intranasally with RSV; 20 μg of CCL5 or CXCL10 in 20 μl were given on days 7, 8 and 9 after infection." (PMID 39749186, 2024).
infection (continued). ", we observed enhanced IFNB and CXCL10 expression and protein secretion during Alpha ΔOrf6 infection of Calu-3 cells compared with WT virus." (PMID 38228858, 2024). "In fibroblasts, major differentially expressed immune-related genes included Cxcl10, Cccl7, and C3, which participate in anti-infectious immunity by immune cell recruitment during infection." (PMID 37478901, 2024). "A protein array used to detect key cytokines in the supernatant of RRV- and Ro1845-infected cholangiocytes revealed CXCL9 and CXCL10 to be the most prevalent cytokines released following RRV infection after normalization to mock-infected supernatant." (PMID 38860860, 2024). "In the early stage of infection (7 dpi), both the cdh1Δ mutant and CDH1OE strain infections were shown to stimulate lung tissue to secrete greater levels of the Th1 chemokine Cxcl10, which is known for its direct killing activity against C. neoformans." (PMID 39728387, 2024). "Among upregulated genes, Cxcl10 showed a 15-fold increase at day 3 post-infection (D3) and a 1300-fold increase at D6." (PMID 39057755, 2024). "IP10 (interferon gamma-inducible protein 10), also known as CXCL10, is a chemoattractive cytokine that attracts inflammatory cells, especially T lymphocytes, to the site of infection." (PMID 38251391, 2024). "With the understanding that RRV and Ro1845VP4-G446R can induce the murine model of biliary obstruction, we wanted to evaluate CXCL9 and CXCL10 levels in vivo following infection." (PMID 38860860, 2024). "Overall, these data show reduction of MMP-9 and CCL2 concentrations, and an induction of IFN-β and CXCL10 across time, as a result of infection." (PMID 40295794, 2024). "Infection of microglia was associated with a sharp increase in CCL2 and CXCL10 chemokine gene expression and the activation of many type I interferon stimulated genes (MX1, ISG15, ISG20, IFI27, IFITM3 and others)." (PMID 38737767, 2024). "The absolute numbers of parenchymal CD19+ B cells and both CD4+ and CD8+ T lymphocytes were increased in Cxcl10+/+ mice at day 4 post infection compared to uninfected control mice." (PMID 39803542, 2024). "By 24 hours after infection, we also detected increased expression of genes involved in a broader inflammatory response, including Ccl2, Cxcl9, Cxcl10, and Ccl7, which were upregulated across the major LNSC subsets." (PMID 38194268, 2024). "Reduced host responses to BA.4 and BA.5 infection were also evident at the level of IFNβ and CXCL10 secretion." (PMID 38228858, 2024). "The cytokine response to infection with MR766 or PRVABC59 is mainly limited to CXCL10, IL-6/8/12, and CCL5." (PMID 39057782, 2024). "aureus with knockdown of CXCL9, CXCL10, or both of them was collected after 12 h of infection before treatment with neutrophils or macrophages." (PMID 39001897, 2024). "In CNS EV-71 infection, cytokines such as IL-6, IL-8, and CXCL10/IP-10 have been observed in the CSF, which correlates with an increase in the recruitment of monocytes and neutrophils in this fluid." (PMID 38248274, 2024). "High levels of cytokines and chemokines, including CXCL10/IP-10 and IL-1β, were observed in the nasal wash fluid of the primary infection group (DMEM-BA.1), but these were lower in reinfected animals." (PMID 36633406, 2023). "Several plasma cytokines had an increased fold change following infection with the most robust increases observed with CXCl10, TNFα, IL-10, and IL-1RA, corroborating previously published data." (PMID 37857783, 2023). "High levels of CXCL10/IP-10 and IL-1β were observed in the nasal wash fluid and lungs of the primary infection groups, but the levels were lower in reinfection animals." (PMID 36633406, 2023). "Both the upper and lower airways responded to the infection by all VoCs, but with a tissue-specific inflammatory signature: in the lungs, Mx2, Il-6, Cxcl10 and Il-10 were upregulated for all VoCs, and the highest in SARS-COV-2 Wuhan-infected animals." (PMID 37495586, 2023).
infection (continued). "A significant increase of CXCL10 mRNA levels in whole blood was also observed after infection with the genotype I attenuated isolate OURT88/3, but at lower levels than observed after infection with the genotype I virulent isolate Benin97/1." (PMID 36680273, 2023). "As modulation of host genes by the Omicron subvariants infection in the lung periphery area, upregulation of Cxcl10, Isg15, and Mx-10 expression was observed in the BA.5-infected hamsters." (PMID 37488344, 2023). "Quantitative PCR (qPCR) analysis showed that PTK2B knockdown significantly attenuated the transcriptional levels of antiviral genes such as IFNB1, IFIT1 and CXCL10 induced by HSV1-GFP infection or by transfection with human telomeric DNA (HT-DNA)." (PMID 37989995, 2023). "High levels of chemokines, including CCL2, CCL11, and CXCL10, were found in the cerebral spinal fluid (CSF) of the mouse model of mild COVID-19 and persisted during infection." (PMID 37791071, 2023). "NanoS100–SwIAV vaccine upon the SwIAV-H1N1-OH7 and H1N1 pandemic virus challenge infection stimulated the population of CXCL10+CD80/86+-activated monocytes in the draining TBLN and in the systemic compartment." (PMID 38006039, 2023). "We observed that ASFV-Δ110-9L/505-7R infection increased HT-DNA-triggered transcription levels of Ifn-b, Isg56, Cxcl10, and Isg15 compared with ASFV-WT." (PMID 37162350, 2023). "Previous research has been reported that KC induces intrahepatic Endo cell injury by producing Cxcl10, which leads to intrahepatic inflammatory response upon infection." (PMID 37808269, 2023). "We found that the recruitment of leukocytes into the brain is specifically determined by STING-dependent IFNβ induction in the brain endothelium via induction of CXCl10 (trajectory B of IFNα/β production during infection)." (PMID 37791071, 2023). "At the viremia peak, the cytokine storm partially resolves with persistent elevation of some cytokines such as TNF, IFNɣ, IL-22, and CXCL10 above pre-infection physiologic levels and into the chronic phase in untreated infections." (PMID 36776887, 2023). "CXCL10 is involved in the regulation of multiple proinflammatory cytokines by stimulating the activation and migration of immune cells to the site of infection." (PMID 36774490, 2023). "Here, we also show that USUV and WNV BBB direct infection led to the release of potent chemoattractants such as CXCL10, CCL5 and CCL2 in vitro and in vivo." (PMID 36495563, 2023). "While the levels of both mRNA and secreted protein for IL-1α and CXCL8 increased in response to infection, the levels of CXCL10 and CCL20 in the culture supernatant decreased." (PMID 37067432, 2023). "In line with mRNA expression changes, hypoxia markedly enhanced secretion of CCL2 and CXCL10 upon infection with SARS-CoV-2." (PMID 37377965, 2023). "Based on our observations, we propose a novel mechanism by which A. fumigatus melanin suppresses host innate immunity to promote infection by binding to and removing CXCL10 and CCL20 from the extracellular environment." (PMID 37067432, 2023). "Gamma variant also showed sustained elevated CXCL10 and CCL2 chemokines compared to Ancestral infection." (PMID 37507719, 2023). "The IFNγ-inducible chemokine receptor CXCL10 expressing myeloid cells recruit CXCR3 expressing activated Th1 lymphocytes to the sites of infection/inflammation." (PMID 38006039, 2023). "qPCR results showed that Ptk2b deficiency dramatically reduced mRNA levels of Ifnb1, Ifit1 and Cxcl10 stimulated by HSV1-GFP or VSVΔM51-GFP infection." (PMID 37989995, 2023). "In blood neutrophils, in the steady state (e.g. Myc, H2-DMb2, H2-M3, H2-Q7...) but also during infection e.g. Cxcl10, H2-D1, C4a, Psme1, Stat1, Psme2, more genes were upregulated in neutrophils from female mice." (PMID 38179044, 2023). "Second, we knocked down Ptk2b in mouse macrophages RAW 264.7 cells and found that Ptk2b knockdown significantly impaired mRNA levels of Ifnb1, Ifit1 and Cxcl10 induced by infection with HSV1-GFP." (PMID 37989995, 2023).
infection (continued). "This can lead to unresolved chronic inflammation in PCS patients, with elevated levels of C-X-C motif chemokine ligand 10 (CXCL10), interleukin-6 (IL-6), and D-dimer even months after the acute phase of infection." (PMID 37507580, 2023). "Accumulating evidence suggests that DMI and OI reduce the infection-induced inflammatory responses and the release of chemokines CXCL10 and CCL2." (PMID 36882813, 2023). "In later stages, significantly higher serum levels of CXCL10 were detected in patients with prolonged post-infection fatigue (>6 months) after symptomatic WNV infection." (PMID 36992514, 2023). "In the context of convalescent infection, the presence of CD57+FcεRIγ− populations was associated with HCMV IgG and CXCL10 (IP-10) levels." (PMID 37923825, 2023). "This can limit clinical translation especially when candidate biomarkers such as CXCL9 and CXCL10 are identified in a wide range of pathologies such as acute rejection, infection, ATN and IFTA." (PMID 37993798, 2023). "At day 10 after infection, all inflammatory mediators had decreased to levels below 10 pg mL−1, except for CXCL10, which was detected in BAL from both WT (38.2 ± 55.1 pg mL−1; n = 8) and mGBP1−/− mice (38 ± 52.6 pg mL−1; n = 10)." (PMID 36744765, 2023). "Murine models with knockouts for the IFNα receptor showed partial protection from experimental CM post-infection by mechanism of reduced T-cell-associated cytokines including CXCL9 and CXCL10, thus highlighting the importance of IFNα in CM development." (PMID 36844403, 2023). "qPCR results indicated that PTK2B overexpression significantly enhanced the mRNA levels of Ifnb1, Ifit1 and Cxcl10 induced by infection with HSV1-GFP or VSVΔM51-GFP in MEFs." (PMID 37989995, 2023). "As detected by qRT-PCR, CXCL10 mRNA increased in response to infection, consistent with the LEGENDplex screen." (PMID 37724882, 2023). "The results indicate that LGP2 knockdown (siRNA si-2 shows the best inhibition effect was chosen) significantly increases the mRNA levels of IFNβ, ISG56, Mx1 and IL6 at multiple post infection time points, and IκBα and CXCL10 at 24 hpi." (PMID 37656756, 2023). "The first cluster was the 14 gene cluster highly up-regulated throughout infection containing Cxcl10 (cluster III), it correlated highest to “defense response to virus” with 10 common genes (P = 3.7E-25)." (PMID 38107402, 2023). "Infection by all three viruses resulted in similar levels of secreted protein levels of CXCL10, CXCL11, and IFN-β." (PMID 37766212, 2023). "Immediately after infection, there is an upregulation of C–X–C motif chemokine ligand 10 (CXCL10) and IFN-γ, which induces CXCL10 expression, with the highest amounts of inflammatory mediators observed just before BBB disruption." (PMID 37775774, 2023). "CXCL10 expression was highly detected in neurons and microglia over 9 days of infection with both CVS-B2c and DRV-Mexico in mouse brain suggesting the neuro-glia communication response." (PMID 37692167, 2023). "There is a clear reduction of these IFN-γ-inducible chemokines (CXCL9 and CXCL10) in the serum upon infection after anti-IFN-γ." (PMID 37205446, 2023). "In the nasal turbinates, Wuhan/ΔORF7ab infection also induced a higher expression of Mx2, but also Il-6, Cxcl10, Tnf-α and Il-10." (PMID 37495586, 2023). "The results revealed that CXCL8 and CXCL10 cytokine expressions were significantly increased from 8 h post-infection while TNF cytokine level remained similar after infection." (PMID 37695039, 2023). "In AGM, the expression of Ccl2, Ccl3, Ccl4, Ccl7, and Ccl8 together with Cxcl10 and Cxcl11 also increases during infection, although more rapidly and with a more marked expression in nonpolarized rAM than in hamsters." (PMID 37350967, 2023).
infection (continued). "The genes encoding for markers of inflammation, namely Tnf, Il1b, Il6, Il23a, and Cxcl10 were induced with infection in Tln1fl/fl mice and significantly decreased in the colon tissues from infected Tln1Δmye mice compared to infected Tln1fl/fl mice." (PMID 38102166, 2023). "Infection with all variants induced elevated pro-inflammatory chemokine expression such as CCL2 and CXCL10 at 2 dpi but elevated expression was sustained longer in Alpha- and Gamma-infected tissues as observed at 5 dpi compared to Ancestral." (PMID 37507719, 2023). "WT, MyD88 KO, and MAVS‐KO THP1 cells produced low levels of CXCL10 at baseline, and these were increased after infection with VZV (Fig EV1D)." (PMID 35670106, 2022). "mRNA levels of several proinflammatory cytokines and chemokines (MDA5, CCL2, RIG-I, and CXCL10) were generally decreased at 1 or more times after infection, but only differences in RIG-I and MDA were statistically significant." (PMID 36378534, 2022). "Next, we evaluated the presence of soluble polypeptides for IFNγ, IL-1β, IL-4, IL-6, IL-8, IL-10, CXCL10, and TNFα in serum of animals following infections with Att-S74-T3Bo and Vir-S74-T3Bo." (PMID 36466866, 2022). "In response to ocular HSV-1 infection, pro-inflammatory cytokines including IL-1, IL-6 and chemokines including CCL2, CCL3, CCL5, CXCL1, CXCL2, CXCL9, and CXCL10 are produced rapidly following infection by resident cells and infiltrating leukocytes." (PMID 36685562, 2022). "Our analyses indicated that despite the presence of baseline inflammation, 2 yr old mice had significantly lower induction of innate immune genes at 2 days post-infection, including Il6, Ccl4, Cxcl10, Rig-I, Irf7, Ifna2, Oas1b, and Mx2." (PMID 36679892, 2022). "Expression of the CXCL10 gene in the high-dose group was 16-fold higher than uninfected controls at 4 weeks post infection and remained elevated (~7-fold) at 7 weeks post infection; but the expression levels in the medium- and low-dosed ferrets remained low." (PMID 36051240, 2022). "For instance, CXCL10 production was increased early after infection and reached its peak with the appearance of MeV-specific IgM antibodies, which later declined." (PMID 36366543, 2022). "Treatment with DI resulted in a modest reduction of HA expression early in infection and a marked reduction of CXCL10, IL6, and IFNB expression." (PMID 35025971, 2022). "Deletion of 4b protein led to a significant reduction in the expression of IFNß, pro-inflammatory cytokines (IL-6 and IL-8) and chemokines (CCL2 and CXCL10) in relation to MERS-CoV-MA-WT infection." (PMID 36129908, 2022). "Elevated CXCL10 levels were reported in patients with SARS or Middle East respiratory syndrome (MERS) as early as 2–3 days post-infection." (PMID 36366543, 2022). "Local immune responses to RV16 infection include the release of interferons and other pro-inflammatory mediators such as CXCL-10 and CXCL-8 leading to infiltration of inflammatory cells." (PMID 36296939, 2022). "As expected, SARS-CoV-WT infection induced at 2 days p.i. in the lungs a significantly higher expression of proinflammatory cytokines (CXCL10, CXCL2." (PMID 35229638, 2022). "It has also been shown that host immune response genes, including IL-4, CXCL10, IL-6, TNFα and IFNγ, are more active with NiV Malaysia infection compared to NiV Bangladesh." (PMID 35632678, 2022). "When comparing the samples from the patients with different infection severities of the same genetic variant, we noted differences in the CCL7/MCP-3, CXCL9/MIG, and CXCL10/IP-10 concentrations." (PMID 36012323, 2022). "Consistently, overexpression of miR-543 significantly increased the Ifnb1, Ifna4, and Cxcl10 mRNA levels after infection with SeV, VSV or stimulation with 5’PPP-RNA compared with the NC group in macrophages." (PMID 36028484, 2022).